CXCL9 (C-X-C motif chemokine ligand 9)
Diseases named in the same sentence as CXCL9 in open-access papers (continued):
Sharing a sentence is not in itself a finding about the gene and the disease.
type 2 diabetes (6 papers, 2012 to 2025). "After merging and filtering across datasets, 13 genes were found to be consistently upregulated in both ulcerative colitis and type 2 diabetes, with CXCL9, S100A8, CXCL10, CHI3L1, and SLC6A14 showing the most significant alterations." (PMID 41155631, 2025). "Overall these data highlight that the simultaneous presence of CHC and type 2 diabetes induces an evident increase of the following proinflammatory cytokines: IL-1α, IL-2R, IL-12, IL-18, CXCL9, MIF and HGF." (PMID 22745767, 2012). "A final group of five biomarkers (CXCL9, IL-2RB, MMP-10, STAMBP, TNF-α) showed positive associations with changes in CES-D in people with type 2 diabetes but without significant effect modification (pinteraction ≤ 0.18)." (PMID 40624224, 2025).
Chagas cardiomyopathy (5 papers, 2012 to 2025). A disease of the cardiac muscle developed subsequent to the initial protozoan infection by trypanosoma cruzi. "Derived allele at rs3921 and CXCL9 rs10336 also turned out to boost CXCR3 expression, in addition to that of the respective genes, in patients with severe progression of Chagas cardiomyopathy." (PMID 27551316, 2016).
CNS lymphoma (5 papers, 2018 to 2024). "Studies in rapidly progressing CNS lymphoma (CNSL) have recently confirmed the excellent diagnostic utility of CXCL13 as well as CXCL9 as predictors of diagnosis, severity of the clinical presentation, and response to therapy." (PMID 38674602, 2024). "CSF-CXCL13 is discussed to be a helpful diagnostic biomarker together with CXCL9, β2-microglobulin, soluble interleukin-2-receptor, and interleukin-10 in CNS lymphoma." (PMID 38203597, 2023). "In primary CNS lymphoma, pericyte-derived CXCL9 and CXCL12 increase tumor-infiltrating lymphocytes, including CD8+ T cells." (PMID 35439170, 2022).
encephalitis (5 papers, 2016 to 2025). An acute inflammatory process affecting the brain parenchyma. "The elevated levels of IL-10, IL-6, IL-8, TNFα (cytokines) and CCL2 and CXCL9 (chemokines) in monocytes may help in predicting the pathogenicity of CHPV causing encephalitis and possible entry into the central nervous system." (PMID 27628855, 2016). "Three studies with 270 encephalitis subjects and 70 control subjects reported the CSF concentration of the CXCL9." (PMID 36048783, 2022). "CXCL9 and CXCL10 are hallmarks of many viral CNS infections including encephalitis caused by HSV-1 and meningitis caused by HSV-2." (PMID 30777092, 2019). "The overall effect shows the CSF concentration of the CXCL9 is higher in encephalitis than in control, whereas non-significant (SMD, 2.50; 95% CI, -0.15–5.16; P = 0.06)." (PMID 36048783, 2022). "CCL19, CXCL8, CXCL9, and CXCL10 were significantly increased compared to CSF from control patients and compared to levels in serum in patients with encephalitis, meningitis, and Ramsay Hunt syndrome whereas CXCL11 was only increased in CSF in VZV meningitis patients." (PMID 30777092, 2019). "We demonstrate that CNS complications caused by VZV virus are associated with highly elevated CSF levels of the chemokines CCL19, CXCL8, CXCL9, CXCL10, and the matrix metalloproteinase MMP-2 in patients with different CNS manifestations such as encephalitis, meningitis, and Ramsay Hunt syndrome." (PMID 30777092, 2019).
endometrial cancer (5 papers, 2017 to 2025). Primary or metastatic malignant neoplasm involving the endometrium (mucous membrane that lines the endometrial cavity). "In endometrial carcinoma, a positive correlation between CXCL9 and JCHAIN was observed, with JCHAIN promoting cytotoxic function." (PMID 41010015, 2025). "Likewise, in another study, CXCL9 was upregulated in endometrial cancer, and its expression was found to be positively correlated with the infiltration of immune cells (T cells, B cells, NK cells, dendritic cells, macrophages) in the TME." (PMID 40673486, 2025). "Using the eQTL definition and applying an FDR correction (FDR ≤ 10%), a positive association between monokine induced by gamma interferon (MIG/CXCL9) and non-endometrioid endometrial cancer risk was observed (3.73, 1.86 to 7.47, p = 2 × 10−4)." (PMID 35012533, 2022). "Whether secretion of growth factors (TGFβ, GAS6, FGF5 and HGF), cytokines and chemokines (IL-6, CXCL9) from CAFs,32 may affect aggressiveness and thereby associate with recurrence of endometrial cancer, is not known and could be investigated in future studies." (PMID 37146405, 2023).
endothelial dysfunction (5 papers, 2024 to 2025). In vascular diseases, endothelial dysfunction is a systemic pathological state of the endothelium (the inner lining of blood vessels) and can be broadly defined as an imbalance between vasodilating and vasoconstricting substances produced by (or acting on) the endothelium. "Elevated CXCL9 levels in cardiovascular disease are associated with metabolic changes in endothelial cells, contributing to endothelial dysfunction." (PMID 40650062, 2025). "Its involvement in vascular aging and endothelial dysfunction is supported by preclinical models showing that CXCL9 silencing can mitigate senescent phenotypes and restore vascular function." (PMID 41419927, 2025). "Descriptive profiling of these biomarkers, including CXCL9, angiopoietin-2, and soluble E-selectin, suggests their potential value in understanding endothelial dysfunction, macrophage activation, and immune dysregulation in MIS-C." (PMID 40430232, 2025). "Moreover, emerging biomarkers such as copeptin, CXCL9, angiopoietin-2, and vitamin D have been investigated for their role in endothelial dysfunction, immune dysregulation, and clinical severity." (PMID 40430232, 2025). "CXCL9 may exacerbate endothelial dysfunction with age, and its role and that of other CXC chemokines in cardiovascular pathology have been demonstrated in previous clinical studies." (PMID 38731215, 2024). "Cytokines such as TNF-α, IL-6, IL-17A, CXCL9, CXCL10, and VCAM-1 are often elevated in both MASLD and SAH, playing crucial roles in immune cell recruitment, endothelial dysfunction, and fibrogenesis." (PMID 40977717, 2025).
hypertriglyceridemia (5 papers, 2023 to 2025). A laboratory test result indicating elevated triglyceride concentration in the blood. "The diagnostic criteria for HLH in adults includes five of the following nine findings: fever, splenomegaly, bi‐cytopenia, hypertriglyceridemia, hemophagocytosis in bone marrow studies, low or absent natural killer cell activity, elevated ferritin, soluble CD25 or CXCL9 levels." (PMID 37065170, 2023).
meningitis (5 papers, 2019 to 2025). A disorder characterized by acute inflammation of the meninges of the brain and/or spinal cord. "have also found inflammatory markers elevated in the CSF during VZV-related meningitis, including interferon gamma, interleukins IL-6, IL-8, IL-10, IL-17F, IL-1RA, chemokines CXCL-9, CXCL-10, CCL-2 and G-CSF." (PMID 40416981, 2025). "High levels of CXCL9 and CXCL10 are detected in CSF of herpes simplex encephalitis and meningitis patients, whereas CXCL11 is exclusively found in herpes simplex meningitis patients." (PMID 30777092, 2019).
non-alcoholic steatohepatitis (5 papers, 2013 to 2025). "Our research group has previously demonstrated that DM509 treatment to non-alcoholic steatohepatitis mice decreased liver CXCR3, CXCL9, CXCL10, TNFα, IL-1β, and TGF-β expression." (PMID 38235144, 2023).
osteoarthritis (5 papers, 2013 to 2025). A noninflammatory degenerative joint disease occurring chiefly in older persons, characterized by degeneration of the articular cartilage, hypertrophy of bone at the margins and changes in the synovial membrane. "GSK3858279, an anti-CCL17 monoclonal antibody, has shown efficacy in relieving osteoarthritis-associated pain, and CXCL9 inhibition has demonstrated therapeutic potential in ulcerative colitis." (PMID 40564127, 2025). "Even though these results do not provide implicit evidence for a causal link between CXCL9 and OA progression, they pointed towards a potential role of this chemokine in degenerative joint disease." (PMID 40047894, 2025). "Together with the reduced synovitis scores observed histologically, these combined results suggest that CXCL9 may influence the progression of OA by modulating at least some aspects of the vast array of pro-inflammatory responses in degenerative joint disease." (PMID 40047894, 2025).
Sjögren’s syndrome (5 papers, 2018 to 2024). "Cxcl9 has been implicated in several contexts in Sjögren syndrome." (PMID 30347820, 2018). "In human studies, salivary gland epithelial cells isolated from healthy individuals and treated with anti-SSA/Ro antibodies isolated from Sjögren syndrome patients showed an increase in the expression of Cxcl9 among genes encoding other inflammatory cytokines and chemokines." (PMID 30347820, 2018). "Cxcl9, Ccl19 and Epsti1 have been implicated in Sjögren syndrome in humans or animal models." (PMID 30347820, 2018). "Cxcl9 gene expression levels were also higher in conjunctival epithelium from Sjögren syndrome patients compared to controls." (PMID 30347820, 2018). "Cxcl9 was upregulated in salivary glands in several mouse models of Sjögren syndrome and in lacrimal glands of the NFS/sld model of Sjögren syndrome." (PMID 30347820, 2018). "CXCL9 protein levels (along with CXCL10 and CXCL11) were elevated in tears and conjunctival epithelium from Sjögren syndrome patients compared to controls samples." (PMID 30347820, 2018). "Additionally, a correlation was found between the expression of the CXCL9 gene and the EULAR Sjogren’s Syndrome Disease Activity Index (ESSDAI), as well as with immunoglobulin G (IgG) levels and erythrocyte sedimentation rate (ESR)." (PMID 38229121, 2024). "This study aimed to investigate the serum and expression levels of C-X-C motif chemokine ligand 9 (CXCL9), CXCL10, CXCL11, and CXC receptor 3 (CXCR3) in minor salivary glands (MSGs) of patients with primary Sjögren’s syndrome (pSS), and to explore their correlations with clinical parameters." (PMID 38900301, 2024). "CXCL9 proteins are predominantly expressed in the ductal epithelium adjacent to lymphoid infiltrates in the Sjögren's syndrome salivary gland but are not expressed in the normal salivary gland (Ogawa, Ping, Zhenjun, Takada, & Sugai, 2002)." (PMID 28885690, 2018).
dengue virus infection (4 papers, 2014 to 2020). "Although the IP-10 and CXCL9 are considered associated with increase in vascular permeability which leads to severe dengue fever, they are only consider as the risk factors contributed to the severity of the dengue infection." (PMID 29651328, 2018). "Together with other chemotactic effectors (CXCL9/10/11) and immune cell response-modulating cytokines (IL-6, IL-7 and BAFF), RANTES has been associated with immune enhancement and increased vascular permeability following dengue virus infection." (PMID 28006034, 2016). "Although all three ligands are induced by dengue virus infection, CXCL9 and CXCL11 could not compensate for the absence of CXCL10 in Cxcl10-/-mice." (PMID 24939012, 2014).
eosinophilia (4 papers, 2009 to 2023). "CXCL9 was associated with severity of interstitial features characteristic of AIN, including interstitial infiltrate and tubulitis, but not with the degree of interstitial eosinophilia or tubular injury." (PMID 37395276, 2023).
fatty liver (4 papers, 2015 to 2025). "CXCL9 was elevated in patients with autoimmune hepatitis and mice with fatty liver, indicating that CXCL9 inhibition is a potential strategy in NAFLD treatment." (PMID 31269941, 2019). "Expression levels of C-C chemokine receptor 1 (CCR1) and chemokine (C-X-C motif) ligands 9, 10, 14 (CXCL9, CXCL10, and CXCL14) are increased in livers during HFD-induced hepatic steatosis." (PMID 25887406, 2015).
glaucoma (4 papers, 2012 to 2024). Increased pressure in the eyeball due to obstruction of the outflow of aqueous humor. "Recent evidence suggests that CXCL9 is an important marker of inflammation and plays a key role in the development of age-associated diseases, such as neurodegeneration, chronic kidney disease, glaucoma and various inflammatory diseases." (PMID 37691946, 2023). "Among these cytokines, the median concentrations of IL-10 (p=0.050), IL-12 (p=0.003), IFN-γ (p=0.002), IFN-α (p=0.034), IL-9 (p=0.032), and CXCL9 (p=0.006) were also significantly higher in the glaucoma group." (PMID 22355254, 2012). "A total of 6 cytokines were found significantly elevated in glaucoma samples compared to controls, which include IL-10, IL-12, IFN-γ, IFN-α, IL-9, and CXCL-9." (PMID 22355254, 2012). "When the glaucoma group was further separated into POAG and PACG, we found significantly elevated concentrations of IL-12 (p=0.011), IFN-γ (p=0.005), and CXCL9 (p=0.047) in the POAG aqueous compared to the cataract group." (PMID 22355254, 2012). "Aqueous obtained from the glaucoma patients showed increased concentration of interleukin (IL)-9 (p=0.032), IL-12 (p=0.003), interferon (IFN)-α (p=0.034), IFN-γ (p=0.002), monokine induced by interferon-gamma (MIG or CXCL9) (p=0.006), and IL-10 (p=0.050), compared to the cataract group." (PMID 22355254, 2012).
hyperferritinemia (4 papers, 2023 to 2025). "Accordingly, IL-18/CXCL9 ratios were significantly higher in rheumatologic-associated hyperferritinemia compared to the other two subgroups." (PMID 39264477, 2024).
inflammatory skin disease (4 papers, 2017 to 2023). Inflammatory skin disorders covers a broad category that includes many conditions ranging in severity, from mild itching to grave medical health complications These disorders are common in people of all ages and races. "Another previous study reported findings similar to our data, showing differences in the expression of CXCL9, CXCL10, and CXCL11 in different types of inflammatory skin disease, including lichen planus, chronic discoid lupus, and psoriasis." (PMID 28436448, 2017). "Specifically, chemokines CXCL9, CXCL10, and CXCL11 were involved in the T cell recruitment and infiltration in inflammatory skin diseases." (PMID 28427244, 2017). "The IFN-γ-induced chemokines CXCL9 (chemokine C-X-C motif ligand 9), CXCL10, and CXCL11 recruit Th1 cells by binding to CXCR3 (chemokine C-X-C motif receptor 3) on the cell surface and significant infiltration of Th1 cells are seen in inflammatory skin diseases." (PMID 36742296, 2023).
kidney damage (4 papers, 2012 to 2025). "Additionally, plasma IL-8, CXCL9, TNF-α and GDF15 showed significant correlation with kidney damage assessed by decreased eGFR." (PMID 39188767, 2024). "Moreover, CXCL1, CXCL9, β-NGF, C-peptide, GIP and adiponectin are higher only in CHC patients in agreement with previous studies in which these molecules were found elevated only in diabetic patients with complications (nephropathy, retinopathy and atherosclerotic lesions)." (PMID 22745767, 2012).
kidney transplant (4 papers, 2009 to 2023). A surgical procedure in which one or both kidneys from a donor are implanted into a recipient. "During kidney transplant rejection intrarenal RNA expression of Th1-associated ligands CXCL10 and CCL5 have been documented, also increased urinary chemokines CXCL9 and CXCL10 were found during acute rejection compared to stable recipients." (PMID 23717673, 2013). "In summary we suggest CXCL9 (but not CXCL10) testing in urine as an adjunct test to immunodominant DSA characterization in serum for the prediction of late antibody-mediated rejection in clinically well-presenting, but DSA-positive long-term kidney transplant patients." (PMID 32328494, 2020).
Lyme disease (4 papers, 2014 to 2025). Lyme disease (named after the towns in the USA where the disease was first identified) is a bacterial infection caused by Borrelia burgdorferi. "When we compared the levels of serum CXCL9/CXCL10 among the acute Lyme patients with high liver enzyme levels, there was a significant association of high CXCL9/CXCL10 and CCL19 levels with elevated liver enzymes in the acute phase of Lyme disease." (PMID 24740099, 2014). "This is supported by the finding that chemokine (CXCL9 and CXCL10) and cytokine levels can vary in Lyme disease patients depending on the genotype of the infecting B. burgdorferi." (PMID 24740099, 2014). "Previous work has shown elevated levels of CXCL9 and CXCL10 within the EM skin lesion and in the sera of patients with early acute Lyme disease, as well as in the synovial fluid and tissue of patients with Lyme arthritis." (PMID 24740099, 2014). "Similar to our observations, the levels of serum CXCL9 and CXCL10 can vary among acute Lyme disease patients and levels correlate with severity of disease." (PMID 24740099, 2014). "CXCL9, CXCL10 and CCL19 are three prominent chemokines that were elevated in our cohort of acute Lyme disease patients." (PMID 24740099, 2014). "The coordinated elevation of CXCL9, CXCL10 and CCL19 in acute Lyme disease is consistent with an ongoing host immune response in the draining lymph nodes accompanied by the generation of Borrelia - reactive effector T cells and their migration into the site of infection." (PMID 24740099, 2014).
lymph node metastasis (4 papers, 2019 to 2024). "In a separate analysis, low CXCL9 protein expression was associated with increased lymph node metastasis (p = 0.018 and p = 0.036)." (PMID 38957805, 2024). "Further analyses showed that CXCL9 was lowly expressed in patients with more lymph node metastasis according to density in both TC and IM (p = 0.018), percentage quantification in TC (p = 0.043), and percentage quantification in both TC and IM (p = 0.036)." (PMID 38957805, 2024).
multiple myeloma (4 papers, 2017 to 2025). "It it noteworthy that high CXCL9 levels have recently been associated with poor clinical outcome in patients with myeloma." (PMID 28389623, 2017). "The most marked effects were seen for CCL4 and CXCL9 which were increased by 4 and 6 fold respectively in the bone marrow of patients with myeloma." (PMID 28389623, 2017). "High concentrations of CXCL9 and CXCL10 interfere with the infiltration of natural killer (NK) cells into the MM microenvironment and limit their anti-myeloma activity." (PMID 36733370, 2022). "The peculiar multiple myeloma microenvironment, characterized by up-regulated levels of several inflammatory chemokines, including the CXCR3 receptor ligands CXCL9 and CXCL10, limits NK cell positioning into the bone marrow by interfering with CXCR4 function." (PMID 31699153, 2019). "The magnitude of this effect was considerable with the most marked effects seen for CCL4 (CCR4 ligand) and CXCL9 (CXCR3 ligand), which were increased by 4 and 6 fold respectively in the bone marrow of patients with myeloma compared to controls." (PMID 28389623, 2017). "Interestingly, the expression of both CXCL9 and CXCL10 was markedly increased in the bone marrow of the patient groups, and appeared to increase in a progressive fashion during the clinical transition from MGUS to myeloma although a definitive longitudinal study would be needed to confirm this." (PMID 28389623, 2017).